EPCAM (epithelial cell adhesion molecule)
Diseases named in the same sentence as EPCAM in open-access papers (continued):
Sharing a sentence is not in itself a finding about the gene and the disease.
tumor (continued). "This approach requires knowledge of tumor specific proteins, and the protein we used in this study is EpCAM, a transmembrane glycoprotein that is highly expressed in RB tumor cells compared to normal retinal cells." (PMID 23687439, 2013). "During the assay development, however, we found that some of these widely expressed epithelial / tumor markers, such as EpCAM, HER2, and CK19, were detectable in blood samples from some healthy donors by the very sensitive qRT-PCR assay." (PMID 23990866, 2013). "Because of their high content of CD133+/EpCAM+ cells, tumor spheroid cells were proved to be highly tumorigenic upon xenotransplantation compared to their differentiated progeny when equivalent amount of cells were injected." (PMID 23826249, 2013). "EPCAM protein was detected in 42/92 (45.7%) human non-tumor mucosa samples; all samples expressed EPCAM protein at a low level." (PMID 24422715, 2013). "In 42% of the study patients (n=54), we observed a differential EpCAM expression pattern with respect to the centre and the invasion front of the tumor." (PMID 23830302, 2013). "The Muc1 gene is one of the markers included in a commercial test (AdnaTest BreastCancer®) which combines immunomagnetic tumor cell selection targeting EpCAM and MUC1 followed by multiplex RT-qPCR for the transcripts EpCAM, MUC1 and HER2." (PMID 24058517, 2013). "Earlier, we showed that EpCAM is highly expressed in RB tumor cells when compared to the normal retina." (PMID 23687439, 2013). "Expression of EPCAM correlated with age, tumor location, tumor size, Lauren’s classification, depth of invasion, lymph node and distant metastases, regional lymph node stage and TNM stage (P < 0.05)." (PMID 24422715, 2013). "The second function of EpCAM relates to the regulation of proliferation and was in the first place described as a correlation of the expression of EpCAM with areas of proliferation in tumours." (PMID 24009667, 2013). "In regards to overall survival, larger tumor size (≥4 cm) (P<0.001), vascular invasion (P<0.001), intrahepatic metastasis (P<0.001) and the histologic groups of cHC-CC and EpCAM(+)/K19(+) HCC (P = 0.002) were revealed as adverse prognostic factors." (PMID 24086533, 2013). "To additionally test the potential impact of EpCAM expression levels on proliferation, we stained consecutive sections of tumor tissues with the proliferation marker Ki-67 and correlated the staining data." (PMID 23830302, 2013). "Correlating EpCAM expression with KI-67-positive tumor cell nuclei using linear regression, we observed a significant positive correlation in primary tumor samples (p<0.006) as well as in lymph node metastases (p=0.02)." (PMID 23830302, 2013). "In clear contrast to all tumor samples analyzed, normal polarized epithelia had a strict localization of EpCAM on the basolateral membrane." (PMID 23758908, 2013). "KRT19, CEACAM5 and EPCAM mRNA had been reported previously as promising tumor cell markers in LNs from NSCLC patients, whereas SFTPA and SFTPC were novel genes in this context." (PMID 23671585, 2013). "Mononuclear cells isolated from blood and BM were enriched for tumor cells using an antibody cocktail that included EpCAM." (PMID 23634290, 2013). "In intestinal type tumors the EpCAM expression was high in the invasion front in 14% while 31% of the tumors exhibited high EpCAM expression in the tumor centre." (PMID 23830302, 2013). "CD133+/EpCAM+ cells were then propagated and enriched as tumor spheroid cells under stem cell conditions." (PMID 23826249, 2013). "In order to determine the isolation efficiency of rare cells, we spiked plasma-depleted blood at a concentration of 13-24 tumor cells per ml and recovered them with anti-EpCAM MBs." (PMID 23516425, 2013). "In the patient tumor, CD133+/EpCAM+ cells represented the tumor-initiating cells upon xenotransplantation." (PMID 23826249, 2013).
tumor (continued). "Xenotransplants grew in a focal, gland-like manner and expressed EpCAM and Ki-67 in a correlated manner at the edges of tumour areas." (PMID 23383219, 2013). "In order to assess the potential differences in these molecules, CD133high- and CD133low-derived tumours were stained for the standard CD44s, CD44v6, and for EpCAM." (PMID 23150174, 2013). "EpCAM-targeted MBs efficiently (88%) isolated frequent tumor cells that were spiked at 100,000 cells/ml into plasma-depleted blood." (PMID 23516425, 2013). "In preclinical studies, huKS-IL2 demonstrated significant anti-tumor effects when administered intravenously or directly into EpCAM-positive tumors." (PMID 23320927, 2013). "Epithelial cell adhesion molecule (EpCAM) is overexpressed on malignant cells from a variety of different tumors and is considered as a reliable marker for tumor-initiating cells." (PMID 23819113, 2013). "Primary carcinoma cells strongly expressed EpCAM especially at the tumour leading edges, which correlated with areas of proliferation as monitored upon Ki-67 staining." (PMID 23383219, 2013). "Using EpCAM targeted MBs we achieved 88% isolation efficiency of tumor cells spiked at high concentration (100,000 cells/ml) in 1 ml of plasma-depleted blood, and 77% isolation efficiency of rare cells (23 cells/ml) spiked in 7 ml of plasma-depleted blood." (PMID 23516425, 2013). "Catumaxomab, a monoclonal antibody against EpCAM is a trifunctional antibody, which can bind three different cell types, including tumor cells, T cells, and accessory cells (dendritic cell, macrophages, and natural killer cells)." (PMID 23509802, 2013). "Flow cytometric analysis showed that the percentage of CD133+/EpCAM+ cells in P1 xenograft tumors remained in the same range as that in the primary tumor." (PMID 23826249, 2013). "One is expressed by almost all the tumor cells originated form epithelial cells, such as epithelial markers (cytokeratins (CK), epithelial cell adhesion molecule (EpCAM), human epithelial antigen (HEA))." (PMID 23806209, 2013). "A number of tumor-associated or epithelial-specific genes are used in the detection of CTCs of different types of cancer, including CK, Her2, CEA, MUC1, EpCAM, EGFR, hTERT, survivin, c-met, FN1 and several other mRNA markers." (PMID 23599802, 2013). "EpCAM positive cells also have tumor-initiating potential, making it a potential target for cancer therapy." (PMID 23509802, 2013). "It was also reported that the presence of Circulating Tumor Cells (CTCs) with cellular expression of epithelial cell adhesion molecule (EpCAM) was more predictive of clinical outcomes than the WHO grading system." (PMID 23607525, 2013). "Among these characteristics, larger tumor size and more frequent vascular invasion were also more frequently noted in cHC-CCs than in EpCAM(+)/K19(+) HCCs." (PMID 24086533, 2013). "The CD44+/CD24−/EpCAM+ population sorted from these lines has stem-like properties and is able to initiate tumour formation much more readily than the luminal population (CD44+/CD24+/EpCam+)." (PMID 23436775, 2013). "CD133+/EpCAM+ CSCs were enriched under stem cell culture conditions and formed 3-dimensional tumor spheroids." (PMID 23826249, 2013). "The pleiotropic activity of EpCAM, together with high surface expression in some tumor types, makes it a natural candidate for targeting with therapeutic antibodies or antibody–drug conjugates." (PMID 23320927, 2013). "After excluding non-viable cells by propidium iodide staining, approximately 4–6% CD133+/EpCAM+ cells were detected in the tumor tissue, suggesting the presence of putative CSCs." (PMID 23826249, 2013). "CTCs are detected frequently in early-stage NSCLC using a non-EpCAM mediated approach with a wide range noted for a given level of FDG uptake or tumor size." (PMID 23861795, 2013).
tumor (continued). "Focussing only the heterogenic expression pattern of 45%, we noticed that 28% of diffuse type of tumor was presented with higher EpCAM expression in the invasion front while the rest of 17% was presented with higher EpCAM expression in the tumor centre." (PMID 23830302, 2013). "Next we investigated the binding of the MOC31 antibody to EpCAM expressed on the surface of tumour cells in vivo." (PMID 22590529, 2012). "We assessed the role of Notch for the maintenance of tumor initiating pancreatic CD44+/EpCAM+ cells and found that with down regulation of the Notch signalling pathway the expression of CD44 and EpCAM on protein level were dramatically decreased." (PMID 23094026, 2012). "Detection of a CTC using the CellSearch platform is dependent on CTC expression of epithelial markers, namely epithelial cell adhesion molecule (EpCAM) for tumour cell capture and cytokeratin (CK) for tumour cell confirmation." (PMID 22187035, 2012). "The binding affinity of the EpCAM aptamer to RB primary tumor cells, Y79 and WERI-Rb1 cells, and Müller glial cell lines were evaluated with flow cytometry." (PMID 23213278, 2012). "In contrast, 19 colonies grew from a total of 522 cells isolated from MCF7 3C-3 blood samples, showing that the EpCAM-positive population isolated from animals with plakoglobin knockdown tumors contains increased numbers of viable tumor cells." (PMID 22632416, 2012). "The in vitro efficacy of EpCAM×CD3 antibody was tested in a FACS-based cytotoxicity assay using CD3-positive pre-activated PBMCs of healthy donors as effector cells and EpCAM-positive human RB cells as target cells (tumor 1)." (PMID 22328825, 2012). "The EpCAM mRNA and protein expression levels of twelve human cancer cell lines representing six different tumour entities were investigated by qPCR, FACS analysis and immunocytochemistry." (PMID 22590529, 2012). "Most of the primary tumours and metastases were positive for EpCAM, MUC-1 and Her2 but in some cases, EpCAM and especially MUC-1 expression disappeared." (PMID 22591372, 2012). "The individual expression of CD44, CD24, ABCG2, and EpCAM in primary tumor samples ranged from 19% to 64%, 15% to 77%, 2% to 7%, 4% to 65%, respectively." (PMID 22328825, 2012). "When both the CellSearch capture antigen (EpCAM) and the detection antigen (CK) are expressed in tumour, the CellSearch detected CTC number can be zero." (PMID 22187035, 2012). "Recently, tumor-protective immunization has been observed with the high affinity EpCAM-specific surrogate antibody BiLu." (PMID 23134699, 2012). "To analyze the effect of GSI on proliferation of pancreatic CD44+/EpCAM+ cells in xenograft tumors we performed Ki67 staining of xenograft tumor tissues." (PMID 23094026, 2012). "EpCAM is assumed to be downregulated during the journey of epithelial tumor cells in the circulation." (PMID 22530147, 2012). "For the present study we modified a commercially available tumor cell enrichment and detection assay to combine anti-EpCAM and anti-cytokeratin for immunomagnetic CTC enrichment." (PMID 22646670, 2012). "The significant enhanced expression of CSC marker EpCAM on the tumor cells of CR patients is consistent with the epithelial phenotype of that population of cells." (PMID 23056490, 2012). "Intravenously applied radio-labelled anti EpCAM MOC31 antibody was enriched in HT29 primary tumour xenografts indicating that EpCAM binding sites are accessible in vivo." (PMID 22590529, 2012). "Immunohistochemical analysis of tumor cells by the proliferation marker Ki67 revealed that knockdown of EpCAM significantly affected tumor cell invasion into host tissue." (PMID 23110550, 2012). "CDF treatment decreased the relative mRNA levels of HIF-1α, VEGF, IL-6, CD44, and EpCAM in MiaPaCa-2 tumor sphere cells under hypoxic conditions." (PMID 23272057, 2012).
tumor (continued). "EpCAM signals were detectable from 2 tumour cells or more for EpCAMhigh cells (MDA-MB-468, KPL-4) but the detection limit was 10 tumour cells in case of EpCAMlow cells (MDA-MB-231)." (PMID 22591372, 2012). "Elevated EpCAM expression was confirmed amongst other tumour entities in breast, pancreatic, colon, prostate and lung cancer." (PMID 22590529, 2012). "The results show that anti-miR-21 decreased the expression of CD44 and EpCAM in MiaPaCa-2 tumor sphere cells under hypoxic conditions, consistent with the results from CDF treatment." (PMID 23272057, 2012). "Tumor differentiation, however, was different between the EpCAM high and EpCAM low groups (p = 0.024)." (PMID 23216644, 2012). "We observed that a subpopulation of tumor cells in all the samples showed dual expression of EpCAM with CD44, CD24 and ABCG2 individually." (PMID 22328825, 2012). "Twelve human cancer cell lines representing six tumour entities were tested for their EpCAM expression by qPCR, flow cytometry analysis and immunocytochemistry." (PMID 22590529, 2012). "To further determine the effect of GSI on sorted tumor initiating CD44+/EpCAM+ cells, we analyzed the effect of GSI by cell proliferation assay." (PMID 23094026, 2012). "The results obtained in this study show a significant relationship between tumor recurrence rates and pretransplantation EpCAM expression in patients who underwent pre-transplant TACE." (PMID 23216644, 2012). "With one of these models we also investigated the accessibility of EpCAM to antibodies in the primary tumour after i.v. application of the anti EpCAM antibody MOC31." (PMID 22590529, 2012). "It supports prior studies that have identified EpCAM as a marker that best identified HCC-derived cells with tumor forming potential." (PMID 23216644, 2012). "According to their EpCAM expression profile we used lentiviral systems to alter endogenous gene expression and studied the effects on in vitro and in vivo tumor growth." (PMID 23110550, 2012). "As CD133 and EpCAM were the markers that associated with post-TACE status, we wanted to determine if variable expression of these markers predicted tumor characteristics." (PMID 23216644, 2012). "Currently, the epithelial cell-adhesion molecule (EpCAM), represents the antigen of choice for the majority of microfluidic devices that have been developed to capture circulating tumor cells." (PMID 22558290, 2012). "The modulation of selected genes such as BMP7, EpCAM and VCAN entailed an increase in the proteins encoded by them, indicating that high CD157 expression alters tumor cell phenotype." (PMID 22916288, 2012). "Tumor recurrence rates at post-transplantation were 40 % (4/10) in EpCAM high and 0% in EpCAM low post-TACE patients (p = 0.040)." (PMID 23216644, 2012). "The human epithelial cell adhesion molecule (EpCAM) is highly expressed in a variety of clinical tumour entities." (PMID 22590529, 2012). "The main finding of this study is the demonstration of a distinct phenotype of tumor cells (CA125+++EpCAM+++/STAT3+++), as well as stromal cells (CD44+++/Oct4+++) isolated from the ascites of a limited number of CR patients (n = 4)." (PMID 23056490, 2012). "Our results indicate that EpCAM expression is wide-spread over all tumours used making it an ideal target for imaging/therapeutic purposes." (PMID 22590529, 2012). "EpCAM×CD3 possesses potent antitumor activity in vitro by inducing secretion of interleukins and cytokines by pre-activated lymphocytes in the presence of EpCAM-expressing RB tumor cells." (PMID 22328825, 2012). "In contrast, in tumor cells with a mesenchymal phenotype EpCAM expression decreases and the tumor cells grow independently of EpCAM signaling." (PMID 23110550, 2012). "We showed for the first time that gene expression changes in CTCs are very fast and seem to depend on contact with endothelial surfaces or organ systems in vivo, since even i.v. injected tumour cells quickly down-regulated EpCAM." (PMID 22591372, 2012).
tumor (continued). "This contribution describes the expression of EpCAM in 12 human cancer cell lines in vitro and in vivo in related primary tumours that were developed in xenograft models." (PMID 22590529, 2012). "All cell lines were characterized as epithelial (EpCAM+) tumor cells, showing surface tumor marker expression (CEACAM+)." (PMID 23300683, 2012). "To validate the results and test for reproducibility, we tested the efficacy of EpCAM×CD3 on four more tumor samples that were positive for EpCAM." (PMID 22328825, 2012). "Other methods such as EpCAM-coated or mimetic peptide-based magnetic beads have also been used to isolate tumor cells from ascites, but these methods are not only expensive but time-consuming and result in inconsistent low yields of cells." (PMID 23056490, 2012). "Tumour cells showed dynamic changes and down-regulated EpCAM and Her2 while circulating through the bloodstream." (PMID 22591372, 2012). "Yet, all these EpCAM-antibody-based technologies assume that tumor cells of epithelial origin do express the EpCAM antigen." (PMID 22825490, 2012). "We also performed apoptotic assay in these sorted tumor initiating CD44+/EpCAM+ cells in order to study the mechanism by which GSI IX treatment affects cell growth." (PMID 23094026, 2012). "Positive selection of CTCs has been achieved using microfluidic surfaces coated with antibodies against epithelial cell markers or tumor-specific antigens such as EpCAM or prostate-specific membrane antigen (PSMA)." (PMID 23087897, 2012). "Similar observations were made in vivo, where EpCAM-overexpressing mesenchymal tumor cells showed reduced invasive growth and more cell infiltrates of the innate immune system." (PMID 23110550, 2012). "The epithelial phenotype was confirmed by positive immunoreactivity for the epithelial cell adhesion molecule (EpCAM; each >98%) as well as expression of the tumor marker CEACAM." (PMID 23300683, 2012). "Epithelial cell adhesion molecule expression was assessed by IHC in the tumour specimens available from 21 patients within the cohort." (PMID 22187035, 2012). "For most of the cell lines analyzed we found that levels of EpCAM abundance were similar between cells grown in culture (in vitro) and cells grown as a primary tumour in a xenograft model (in vivo) judged by immunoreactivity of the MOC31 antibody." (PMID 22590529, 2012). "Simeone similarly used CD24/CD44/EpCAM to identify a pancreatic CSC population that displayed the ability to form tumor cell spheres as well as enhanced tumor formation in nude mice." (PMID 22570653, 2012). "Collectively these results indicate that EpCAM+/hMAM- cells are tumor-derived cells similar to EpCAM+/hMAM+ cells, but with phenotypic alterations compatible with an EMT state." (PMID 21816090, 2011). "Circulating tumour cell load measured by real-time RT-PCR for EpCAM was increased significantly in the immediate postoperative period." (PMID 21281486, 2011). "Using the IMS method, EpCAM-positive tumour cells were detected in 41 BM samples (17%) with increasing frequency through TNM stages 1–3; 10%, 18% and 22%, respectively." (PMID 21448171, 2011). "This assumption is corroborated by the simple clinical observation that the prognostic impact of EpCAM expression depends on tumour type, disease stage and host antitumour immunity." (PMID 21281469, 2011). "The current study demonstrates that the peripheral blood of cancer patients contains circulating tumor cells other than those normally detected with antibodies to EpCAM and cytokeratin." (PMID 21577258, 2011). "The current study is the first using an EpCAM-based real-time RT-PCR assay to detect, quantify and evaluate the prognostic effect of circulating tumour cells in peripheral blood and peritoneal lavage fluid in any gastrointestinal cancer." (PMID 21281486, 2011). "The CTC detection was performed using ErbB2/EpCAM immunomagnetic tumour cell enrichment followed by multimarker quantitative PCR (QPCR)." (PMID 21587256, 2011).